TPM2 (tropomyosin 2)
Diseases named in the same sentence as TPM2 in open-access papers (continued):
Sharing a sentence is not in itself a finding about the gene and the disease.
cancer (34 papers, 1996 to 2025). A tumor composed of atypical neoplastic, often pleomorphic cells that invade other tissues. "Forced expression of fascin and knock-down of Tpm2 has been previously linked with enhanced migration/invasion in various cancer cell lines." (PMID 40887664, 2025). "The involvement of Tpm2 isoforms and fascin-1 in cancer development and metastasis makes them promising candidates for prognostic markers and potential therapeutic targets." (PMID 40887664, 2025). "Tropomyosins 2 (TPM2) are actin-binding proteins and have been found as a biomarker candidate for certain cancers." (PMID 36823643, 2023). "To demonstrate the single-gene multi-disease survival analysis function, we show the effect of the TPM2 gene on patient survival status in six cancer datasets (which were ‘TCGA-COAD’, ‘TCGA-ACC’, ‘TCGA-BLCA’, ‘TCGA-OV’, ‘TCGA-LIHC’, and ‘TCGA-KIRC’)." (PMID 34113575, 2021). "Of specific interest is the induction of TPM1, TPM2, TNC and POSTN, suggesting a fundamental reprogramming of lung fibroblasts such that the cells exhibit a gene expression profile that is typical for carcinoma-associated fibroblasts." (PMID 25924783, 2015). "Likewise, the gene TPM2, whose splice variants and differential expression have been associated with EMT, cancer, and muscle diseases, is expressed in its muscle-specific isoform near the stromal archetype." (PMID 38674106, 2024). "In addition, it is worth noting that TPM2 also has a particular contribution to promote apoptosis in cancer cells." (PMID 37686101, 2023). "Several studies have suggested TPM2 as a biomarker candidate for certain cancers." (PMID 36823643, 2023). "Studies on the abnormal expression levels of TPM2 in cancer cells are common." (PMID 37686101, 2023). "Recent studies also revealed that TPM2 can exert pro‐ or antitumorigenic roles in cancers, which may be related to the functional specificity of the gene in different kinds of cancers." (PMID 34850589, 2022). "TPM2 is a member of the tropomyosin gene family and is closely related to cytoskeletal functions, such as cytokinesis, vesicle transport, cell proliferation, migration, and apoptosis, and is related to the occurrence of cancer." (PMID 35971319, 2022). "The increased expression of TPM1, TPM2 and TNC indicates a fundamental reprogramming of normal lung fibroblasts such that they exhibited a gene expression pattern that is typically found in carcinoma-associated fibroblasts." (PMID 25924783, 2015). "In addition to the microtubule-interacting kinesins, we identified three actin-binding proteins, MYH1, MYO1G and TPM2, as essential proteins for cancer cell survival." (PMID 23071517, 2012). "In addition to the cancer connections studied here, our results provide clues to the etiology of rare genetic disorders caused by mutations in KIF21A and TPM2." (PMID 23071517, 2012). "In this study, we identified KIF11, KIF20A, KIF21, KIF25, MYO1G, MYH1 and TPM2 as proteins whose depletion causes growth inhibition and non-apoptotic cell death in cancer cells." (PMID 23071517, 2012). "Cytoplasmic Tpm2 isoforms regulate actin bundling activity of fascin-1 by organizing protein composition in the bundles, a mechanism that may contribute to the suppression of metastatic phenotype in cancer cells." (PMID 40887664, 2025). "Since altered expression of fascin-1 and Tpm has been reported in cancer cells, we used in vitro reconstituted actin filaments containing recombinant HMW Tpm2 isoforms and fascin-1 to investigate the mechanism by which Tpms regulate fascin." (PMID 40887664, 2025). "The new studies identify an accomplice role for the interaction between TPM2 and ELANE in promoting LUAD progression and provide potential strategies in the prevention and/or treatment of LUAD and other cancers." (PMID 40199876, 2025).
cancer (continued). "We identified distinct genes including KLK4, FN1, PBOV1, TPM2, and FLNA which are known to be involved in PCa pathways along with IGF1, TPD52, and SRSF1 that are involved in different cancer pathways." (PMID 37218885, 2023). "Other interesting candidates previously related to cancer include CTNND1 and TPM2, for which alternative splicing events in both transcripts have been correlated with cancer, and HAUS3." (PMID 34496885, 2021). "Previous studies of HMW tropomyosins in breast and other cancers have focused exclusively on the gene products of the TPM1 and TPM2 genes." (PMID 28431393, 2017). "Given the roles of Tpm2 and fascin in actin cytoskeleton dynamics, downregulation of TPM2 coupled with upregulation of FSCN1 may collectively contribute to cytoskeletal remodeling, enhancing cancer cell motility, invasiveness, and metastatic potential." (PMID 40887664, 2025).
myopathies (15 papers, 2013 to 2025). "In some cases, muscle weakness in patients with TPM2-associated myopathies is restricted to proximal muscles in infancy but then progresses to include distal muscles in adulthood." (PMID 35579956, 2022). "At present, 14 TPM2 variants have been identified in patients with myopathies and arthrogryposes in which the significance of the variant has not been definitively defined." (PMID 35579956, 2022). "To date, over 30 TPM2 variants have been identified in patients with myopathies and arthrogryposes, but the biochemical properties of only a few variants have been tested." (PMID 35579956, 2022). "Mutations in TPM2 result in a variety of myopathies characterised by variable clinical and morphological features." (PMID 24039757, 2013). "Variants in the TPM2 gene have been associated with a number of different myopathies." (PMID 35052370, 2021). "Various myopathies are known to be caused by this decoupling mechanism and result from variants in other skeletal muscle genes involved in the Ca2+-dependent contraction response, including TPM2, TPM3, and ACTA1." (PMID 32819427, 2020). "We hope that this review will stimulate interest for future work focused on the function of all TPMs, including TPM1 and TPM2 in skeletal muscle and in myopathies." (PMID 37936227, 2023). "Variants in one of the two tropomyosin genes, TPM2 and TPM3, have been associated with a number of different myopathies." (PMID 35052370, 2021). "PYGM gene which encodes myophosphorylase enzyme was also related to HCM, as well as TPM2 gene, which was reported in patients with myopathy and DCM." (PMID 33567613, 2021). "On the other hand, tropomyosin regulates actin dynamics in non-muscle cells and myopathy-associated TPM2 variants disrupt muscle organization, suggesting that TPM2 disorders involve a developmental component in addition to sarcomere dysfunction." (PMID 39311120, 2024). "Two of the TPM2 variants, V129A and E139K, had not previously been identified in patients with myopathies or arthrogryposes, although CM has been linked to the variant E139Del." (PMID 35579956, 2022). "Moreover, WBMRI has recently been shown to be of particular interest in TPM2-related myopathies an in certain forms of distal arthrogryposis such as DA10 or arthrogryposis due to ECEL1 mutations but has not been used in DA2B yet." (PMID 36968005, 2022). "Aberrant TPM2 expression is known to contribute to a series of rare myopathies." (PMID 34850589, 2022). "Further genetic sequencing revealed missense VUS in the glycogen phosphorylase, muscle associated (PYGM) gene (c.580C>T) and tropomyosin 2 (TPM2) gene (c.536C>T), in addition to a missense pathogenic mutation in the valosin containing protein (VCP) gene, confirming the diagnosis of VCP myopathy." (PMID 33567613, 2021). "Although mutations in TPM2 have been associated with different myopathies, it is not known whether these mutations alter the expression of TPM2." (PMID 29183317, 2017). "Although the results may demonstrate the early stages of morphological changes linked to myopathy associated with TPM2 mutations, our human tissue culture model did not reproduce the pathological features observed in patient muscle biopsies." (PMID 24039757, 2013). "A high degree of phenotypic diversity and intrafamilial variability has been observed in TPM2- and TPM3-related myopathies." (PMID 32456280, 2020).
infection (2 papers, 2016 to 2018). The state of being infected such as from the introduction of a foreign agent such as serum, vaccine, antigenic substance or organism. "The genes significantly impacted by infection only in CS included mast cell proteinase-3, γ-glutamyltransferase 5 (GGT5), CD163 as well as those involved in smooth muscle contraction, such as tropomyosin (TPM2), myosin, light chain 9, regulatory (MYL9), and calponin 1, basic, smooth muscle (CNN1)." (PMID 27197554, 2016).
dysostosis (1 paper, 2023). A group of disorders in which the skeletal involvement is predominantly manifested as abnormalities of individual bones or in a group of bones. "We showed a potential association between TPM2 and the uncommon spondylocostal dysostosis phenotype that would require further validation on larger cohort." (PMID 37744435, 2023).
musculoskeletal disorders (1 paper, 2022). "Our assays in C2C12 cells and zebrafish provided additional evidence that the potentially novel TPM2 variants V129A and E139K are pathogenic, and the results argue that A155T is causative of TPM2-related musculoskeletal disorders." (PMID 35579956, 2022). "As part of our ongoing clinical sequencing of patients with musculoskeletal disorders, we identified 2 potentially novel TPM2 variants and 1 recurring variant." (PMID 35579956, 2022). "The TPM2 variants we identified in patients with musculoskeletal disorders caused defects in musculoskeletal system development." (PMID 35579956, 2022). "Transient overexpression proved to be a useful strategy for identifying TPM2-related disease mechanisms, so we used these assays to characterize 3 variants we identified in patients with musculoskeletal disorders." (PMID 35579956, 2022). "Our results argue that one pathomechanism of TPM2-related disorders is disrupted muscle development and that transient overexpression assays can efficiently characterize variants of uncertain significance identified in patients with musculoskeletal disorders." (PMID 35579956, 2022). "TPM2 variants are identified in patients with musculoskeletal disorders." (PMID 35579956, 2022).
TPM2 also shares sentences with these, for which no sentence is quoted: ovarian carcinoma (4 papers); lung carcinoma (3); Calpainopathy (2); centronuclear myopathies (2); gastric cancer (2); heart failure (2); liver cancer (2); alpha dystroglycanopathies (1); asthenozoospermia (1); autosomal dominant disease (1); autosomal dominant nemaline myopathy 4 (1); bipolar disorder (1); bladder urothelial carcinoma (1); bleeding disorder (1); cardiac arrhythmia (1); cardiac disease (1); cardiac hypertrophy (1); cardiovascular diseases (1); Charcot-Marie-Tooth disease (1); Cirrhosis (1); congenital nemaline myopathy (1); distal arthrogryposis types 1 (1); esophageal squamous cell carcinoma (1); familial hypertrophic cardiomyopathy (1); fibrosarcoma (1); gastric adenocarcinoma (1); gastric tumors (1); genetic disorders (1); glioblastoma (1); Hepatic steatosis (1).
A further 17 diseases each share a sentence with TPM2 in 1 paper.